INS (insulin)
Diseases named in the same sentence as INS in open-access papers (continued):
Sharing a sentence is not in itself a finding about the gene and the disease.
Insulin resistance (continued). "Pregnant women with normal glucose tolerance (NGT) can compensate for increasing insulin resistance by increasing the secretion of insulin, while women with GDM have insufficient insulin secretion." (PMID 36528605, 2022). "Insulin resistance impaired glucose uptake in the insulin-sensitive tissues such as skeletal muscle, fat and heart, thus disrupting glucose homeostasis." (PMID 36434695, 2022). "During pregnancies complicated by maternal obesity, both maternal and fetal insulin levels are high in response to maternal hyperglycemia, and the fetuses of obese mothers develop insulin resistance whilst in utero." (PMID 36619540, 2022). "Several experiments have found a strong link of impaired insulin secretion and insulin resistance to HD." (PMID 35154571, 2022). "A strong link between obesity induced insulin resistance and neurodegeneration through brain insulin dysregulation has been demonstrated previously." (PMID 35803940, 2022). "The loss of function of β-cells, which reduces their capacity to raise insulin secretion to compensate for insulin resistance, results in a lower DI." (PMID 35163144, 2022). "The disruption of carbohydrate metabolism, highlighted by many authors, was marked by muscle insulin resistance induced by significant decrease in Akt activation, which promoted the increase in insulin levels and HOMA-IR with all HFD." (PMID 36033104, 2022). "Insulin resistance and raised plasma levels of insulin are responsible for the high androgen concentration in patients with PCOS." (PMID 36678524, 2022). "Compared to a normal pregnancy, GDM patients have a reduced basal and maximum insulin stimulating transport rates (per surface area) by 38 and 60%, respectively, thus leading to insulin resistance." (PMID 36615730, 2022). "Insulin resistance can begin years before symptoms are present, with high insulin levels even in the presence of normal glycemia, as demonstrated in pre-pubertal children with obesity." (PMID 35208257, 2022). "Insulin resistance is characterized by defective insulin signaling through the AKT or ERK signaling pathway." (PMID 36079898, 2022). "Treatment of HepG2 cells with high glucose and palmitate (PA) triggers a significant reduction in insulin signaling leading to insulin resistance." (PMID 35571083, 2022). "T2DM accounts >90% of DM cases globally, and it is characterized by hyperglycemia, low insulin production, and insulin resistance." (PMID 36561297, 2022). "An improvement in insulin sensitivity and insulin resistance and an increase in fatty acid oxidation after intranasal oxytocin use were also reported in that same study." (PMID 35806096, 2022). "Our study did not use a formal insulin clamp so any relationship between insulin resistance and SA timing can only be inferred; however, our data suggest a potential role for insulin, and insulin resistance, in determination of lactation success." (PMID 35405936, 2022). "Both interventions significantly increased insulin production compared with a placebo, but only K citrate improved markers of insulin resistance and sensitivity." (PMID 36432472, 2022). "A certain degree of oxidative stress can reduce insulin sensitivity by suppressing the AKT signaling pathway leading to insulin resistance." (PMID 36358477, 2022). "It would be reasonable that the results of HOMA-IR, an index of insulin resistance (or impaired insulin sensitivity), were a mirror of those of Matsuda’s insulin sensitivity index." (PMID 35658859, 2022). "The activation of the sympathetic nervous system causes skeletal muscle vasoconstriction, which reduces blood flow and insulin‐mediated glucose uptake, thus leading to insulin resistance." (PMID 36470584, 2022). "Hyperinsulinemia is often seen in T2D as a result of insulin resistance, in which an impaired tissue response to insulin results in the pancreas increasing insulin levels to compensate and manage blood glucose levels." (PMID 36531496, 2022).
Insulin resistance (continued). "For example, HOMA reflects the interaction between insulin secretion and hepatic glucose production while MCAi further evaluate the impact of insulin resistance on lipid metabolism." (PMID 35921366, 2022). "Insulin resistance in subjects with IFG is due to increased hepatic insulin resistance while in subjects with IGT it is related to the increased insulin resistance in skeletal muscles." (PMID 36277718, 2022). "Peripheral insulin resistance, for example, is characterised by reduced insulin-mediated glucose uptake and utilisation in muscle and adipose tissue but enhanced fat breakdown in adipose tissue." (PMID 35268696, 2022). "The pro-inflammatory cytokines are said to impair insulin signalling, increase permeability and inflammation in the intestinal epithelium, eventually leading to development of insulin resistance." (PMID 36046745, 2022). "At both ages, women with PCOS had significantly higher BMI, waist circumferences and serum levels of testosterone, CRP, insulin and fasting glucose and greater insulin resistance than reference women." (PMID 36074951, 2022). "We found that adiposity was positively associated with several insulin resistance-related phenotypes including HOMA-IR, fasting insulin, and HbA1c compared with the normal weight (FDR<0.05)." (PMID 35585555, 2022). "T2DM is characterized by insulin resistance and decreased insulin secretion due to pancreatic β-cell failure." (PMID 36248900, 2022). "Before proceeding with further discussion, it is important to consider the issue of “insulin resistance”, namely the reduced cellular response to the hormone insulin." (PMID 34863942, 2022). "It has been proposed that during MS and DM2, insulin resistance (impaired responses to insulin at target tissues due to alterations in the insulin signaling pathway) increases blood glucose levels." (PMID 35448552, 2022). "This impaired brain insulin signalling is known as central insulin resistance, and is characterised as a physiological state that has been observed alongside peripheral insulin resistance." (PMID 35860945, 2022). "In the state of insulin resistance, insulin secretion is increased to compensate, leading to hyperinsulinemia." (PMID 36452893, 2022). "PRF effectively improved dyslipidemia and decreased the fasting blood glucose and insulin levels, resulting in improved glucose tolerance and insulin resistance in HFD-induced obese mice." (PMID 35215514, 2022). "Intestinal SCFAs act on pancreatic beta cells via the bloodstream to promote insulin secretion and improve insulin resistance in adipocytes, thereby contributing to the prevention and treatment of metabolic diseases." (PMID 36079789, 2022). "The present study also shows a positive correlation between the altered lipid profiles, insulin, and insulin resistance in patients with metabolic syndrome." (PMID 35736651, 2022). "The principal index of insulin resistance is the HOMA index, which can be computed as homeostasis model assessment of insulin resistance (HOMA-IR) as (fasting insulin mU/l) × (fasting glucose mmol/l)/22.5." (PMID 36009471, 2022). "Insulin resistance (IR) refers to a state in which the biological effect of a given insulin concentration is reduced." (PMID 36232938, 2022). "Many studies have demonstrated the natural history of insulin resistance (IR) and β-cell insulin secretion in T2DM." (PMID 35454146, 2022). "The endothelium plays a central role in this process as the blockade of vascular inflammation and oxidative stress prevent insulin resistance and increase peripheral insulin sensitivity, respectively." (PMID 36364796, 2022). "HFHC-fed DUSP22HepKO mice also showed higher fasting blood insulin levels and homeostatic model assessment of insulin resistance (HOMA-IR) values than the DUSP22flox mice." (PMID 36209205, 2022).
Insulin resistance (continued). "Insulin resistance, a hallmark of T2DM and obesity, is a clinical condition characterized by the impaired responsiveness of insulin-sensitive tissues to insulin and a compensatory increase in insulin release by β-cells." (PMID 36615728, 2022). "In a rat model of insulin resistance induced by a high-fructose diet, an increase in insulin sensitivity was also demonstrated." (PMID 35885378, 2022). "Reduced tissue insulin sensitivity and glucose intolerance are common manifestations of obesity, insulin resistance, and a prelude to type 2 diabetes." (PMID 36012219, 2022). "FAK is known to have a crucial role in regulating insulin signaling and insulin resistance in peripheral tissues." (PMID 36012331, 2022). "Among several possible alterations that contribute to insulin resistance in insulin target tissues is a chronic elevation of resting intracellular free Ca2+ concentration [(Ca2+)i]." (PMID 35547584, 2022). "The use of a mix of ALC, LC, l-arginine, and NAC was found to reduce insulin resistance and improve insulin sensitivity and the hepatic insulin extraction index in overweight/obese PCOS patients." (PMID 35453430, 2022). "Oral glucose tolerance tests (OGTT) and insulin release tests indicated impaired glucose tolerance and insulin resistance." (PMID 35600576, 2022). "The consumption of 100 g a day of molybdenum biofortified lettuce, for a total of 12 days, was able to reduce fasting glucose, insulin levels and insulin resistance index in the treated group." (PMID 35405964, 2022). "A significant increase of insulin resistance with a decrease in insulin sensitivity were also found." (PMID 36614933, 2022). "Insulin resistance (IR), which is clinically characterized as the inability of insulin to increase glucose uptake and utilization in individuals, is a common condition that has close relationship with metabolic syndrome." (PMID 35281088, 2022). "A significant decrease in both serum insulin levels and insulin resistance measured by HOMA-IR was observed in the group treated with HDVD when compared to the LDVD group." (PMID 36362806, 2022). "Increasing plasma NEFA levels then leads to inadequate insulin secretion and insulin resistance (low insulin sensitivity), together contributing to the development of T2D." (PMID 35399945, 2022). "Higher insulin levels and insulin resistance can contribute to increased uric acid synthesis and reduced renal excretion of urate." (PMID 35406046, 2022). "The association between metabolic syndrome and preeclampsia is established by an abnormal placental accumulation of glycogen, hyperinsulinemia, and subsequent insulin resistance which lead to an impairment of placental insulin signaling." (PMID 35631313, 2022). "This elevated level of inflammation can result in insulin secretion impairment and insulin resistance, leading to metabolic inefficiencies and ultimately, the development of GDM." (PMID 35734372, 2022). "The crosstalk pathway between IGF-1 and insulin signaling plays an important role in hyperglycemia/insulin resistance-induced cardiac hypertrophy and fibrosis in diabetic cardiomyopathy." (PMID 35509833, 2022). "Diabetic patients who received 500mg of resveratrol per day for 4 weeks showed significant decrease in insulin resistance, glucose, and cholesterol level while increasing insulin sensitivity." (PMID 35909524, 2022). "The importance of insulin resistance in BA metabolism has been demonstrated in different studies that showed the concomitant increase of insulin levels and a decrease of FGF19 levels in line with the development of fibrosis." (PMID 36531484, 2022). "A total of 5, 4 and 7 studies reported the effects of probiotics on blood glucose (regarding fasting blood glucose, insulin and insulin resistance, respectively) in patients with NAFLD." (PMID 37105767, 2022). "In obese individuals with insulin resistance, the beneficial effects of a strawberry-based drink at 40 g at breakfast improved insulin sensitivity." (PMID 36365189, 2022).
Insulin resistance (continued). "MGO or MGO-modified proteins affect ß-cell function, interfere with cellular insulin signaling independently of intracellular ROS formation, and induce insulin resistance via modification of AMP-kinase." (PMID 36432614, 2022). "Generally, short-term vitamin D supplementation is likely to reduce insulin resistance via lowering insulin and glucose levels." (PMID 35012626, 2022). "The HFD group showed insulin resistance with higher plasma insulin concentration compared to that in the ND group at 0 and 30 min during OGTT." (PMID 35454963, 2022). "Crosstalk between players of inflammation and oxidative stress contributes to disruption of the insulin signaling pathway and promotes insulin resistance." (PMID 35327570, 2022). "Resistin was negatively correlated with insulin in the blood of the cats studied, which is confusing, since an important role in the pathogenesis of insulin resistance and T2DM has also been indicated." (PMID 36248900, 2022). "Others and we found that obesogenic diet in mice leads to a pre-diabetic metabolic state with higher blood glucose and insulin levels, evolving in insulin resistance due to diet-induced obesity (DIO)." (PMID 35907957, 2022). "It has been proposed that differences in the expression of insulin genes explain the vulnerability of distinct brain regions to the Aβ and Tau pathology, as exacerbated though the development of CNS insulin resistance during AD." (PMID 36117625, 2022). "T2DM is a common chronic illness characterized by insulin resistance and eventually by decreased insulin secretion by pancreatic beta cells, leading to chronic hyperglycemia and associated long-term disease complications." (PMID 35936218, 2022). "Because these mice remained insulin sensitive, the study provides an in vivo demonstration that insulin resistance plays a critical role in the pathogenesis of frank atherosclerosis." (PMID 35457157, 2022). "Decreased level of 5-HT in patients with depression can antagonize the direct inhibition of insulin secretion, leading to insulin dysfunction and insulin resistance, thus forming a vicious cycle between insulin resistance and depression." (PMID 36117653, 2022). "We found that 1e increases glucose uptake in mature 3T3-L1 adipocytes and C2C12 myotubes and ameliorated palmitate-induced insulin resistance in C2C12 cells more significantly than GA via the insulin-dependent Akt pathway." (PMID 35409287, 2022). "Insulin resistance is characterized by reduced insulin sensitivity and impaired oxidation and glucose utilization." (PMID 36438585, 2022). "Insulin resistance occurs when insulin receptors become less sensitive to insulin due to various factors." (PMID 35056765, 2022). "One study has suggested that the increased insulin concentration is a significant independent predictor of type 2 diabetes even after accounting for adiposity and insulin resistance." (PMID 35757631, 2022). "Insulin resistance refers to the lower-than-expected biological effect of insulin, manifested as a disturbance in the uptake and utilization of glucose." (PMID 36158820, 2022). "In high-fat diet-fed mice, IP6K1 promotes obesity and insulin resistance by reducing insulin signaling and thermogenic energy metabolism in adipose tissue and liver." (PMID 35216174, 2022). "PIK3R1 encodes an enzyme with a direct role in insulin signalling and individuals with mutations in PIK3R1 show severe insulin resistance." (PMID 35843982, 2022). "Correspondingly, previous clinical data implicated that circulating clusterin (a) correlates closely with insulin resistance and (b) decreases in line with improving insulin sensitivity in type 2 diabetes." (PMID 36553017, 2022). "TyG, a non-insulin-based insulin resistance index, combined with an indicator of obesity, was significantly associated with HUA risk in both men and women." (PMID 36277703, 2022).
Insulin resistance (continued). "Fasting glucose and fasting insulin concentrations, as well as insulin resistance (HOMA) values, were analysed in normal-weight adults." (PMID 35406013, 2022). "Insulin resistance increases in patients with RA and is associated with accelerated coronary atherosclerosis, and TNF-α antagonists have been shown to improve insulin sensitivity and reduce insulin resistance in patients with RA." (PMID 36060429, 2022). "In the presence of insulin resistance, increased lipolysis produces more free fatty acids, thereby inhibiting the antilipolytic effect of insulin." (PMID 36060656, 2022). "Patients with insulin resistance and type 2 diabetes have increased circulating insulin, and hyperinsulinemia is considered to be one of the major contributors to increased risk of cancer." (PMID 35158824, 2022). "Insulin resistance is a systemic condition characterized by impaired insulin signaling and glucose uptake." (PMID 35682723, 2022). "Patients with Cushing’s syndrome frequently require higher insulin doses to maintain glycemic control due to insulin resistance." (PMID 36422243, 2022). "The polyol pathway is induced, AGE formation progresses, the hexosamine pathway is upregulated, and protein kinase C isoform activation increases, which impairs insulin signaling and leads to insulin resistance." (PMID 36009191, 2022). "If insulin resistance or insulin production defects occur in the body, it will lead to abnormal regulation of adipogenesis." (PMID 35168604, 2022). "Insulin resistance disrupts insulin-mediated suppression of glucose production, and perturbs fatty acid metabolism during accumulation of skeletal muscle triglyceride." (PMID 35216614, 2022). "The worsened insulin resistance in HFD-fed mK293Q mice was further evidenced by an increase in plasma insulin levels." (PMID 37213714, 2022). "The majority of East Asian patients with T2D, including Chinese, show prominent defects in insulin secretion relative to insulin resistance, and β-cell dysfunction plays a key role in the development of T2D among East Asian populations." (PMID 36335348, 2022). "Participants were categorized as Controls, T1D with normal insulin sensitivity (T1D/IS), and T1D with insulin resistance (T1D/IR)." (PMID 35303528, 2022). "Ginsenoside promotes the expression of IRS-1 in the insulin signaling pathway and played a crucial role in alleviating inflammation and insulin resistance in obesity." (PMID 35069931, 2022). "As a result, flavonoids can diminish insulin resistance in insulin-sensitive tissues in a variety of ways, including via modulating the insulin signaling pathway." (PMID 35335923, 2022). "Exercise has been shown to ameliorate insulin action in insulin-resistant individuals by improvement of the pathophysiologic pathways involved in insulin resistance." (PMID 35677551, 2022). "High PTP1B activity can lead to the dephosphorylation of IR and IRS tyrosine and weaken insulin signal transduction, leading to insulin resistance." (PMID 35056765, 2022). "This study also showed significant improvements in β-cell glucose sensitivity and the insulin secretion/insulin resistance index." (PMID 35563495, 2022). "Insulin resistance is typically defined as decreased sensitivity or responsiveness to metabolic actions of insulin, such as insulin-mediated glucose disposal and inhibition of hepatic glucose production." (PMID 36601005, 2022). "Serum insulin measurements would also be extremely valuable when trying to stage histopathological changes, as serum insulin has been demonstrated to be a reliable indicator of insulin resistance in cats." (PMID 35986507, 2022). "Stimulation of NO production in endothelial cells by insulin improves endothelial function and negatively affects insulin resistance." (PMID 36613966, 2022).